ABCA1 (ATP binding cassette subfamily A member 1)
Diseases named in the same sentence as ABCA1 in open-access papers (continued):
Sharing a sentence is not in itself a finding about the gene and the disease.
non-small cell lung carcinoma (4 papers, 2015 to 2024). A group of at least three distinct histological types of lung cancer, including non-small cell squamous cell carcinoma, adenocarcinoma, and large cell carcinoma. "Exposure of the human non-small cell lung cancer lines A549 and H358 to the antiepileptic drug valproate led to downregulation of ABCA1 mRNA and ABCA1 protein levels through a histone deacetylase 2-(HDAC2)-mediated mechanism." (PMID 34977908, 2021). "When in combination with cisplatin, it potentiated its effects on non-small cell lung cancer cells by decreasing the ATP-binding cassette transporter 1 (ABCA1) activity through HDACII inhibition." (PMID 32466248, 2020). "Finally, the antineoplastic agent gefitinib reduced ABCA1 protein content in various non-small cell lung cancer cell lines." (PMID 34977908, 2021). "Furthermore, miR-106a confers cisplatin resistance through targeting ABCA1 (adenosine triphosphatase-binding cassette A1) in NSCLC (non-small cell lung cancer) cells." (PMID 25760076, 2015). "In non-small cell lung cancer (NSCLC) the efficacy of chemo-immunotherapy is affected by the high expression of drug efflux transporters as ABCC1 and by the low expression of ABCA1, mediating the isopentenyl pyrophosphate (IPP)-dependent anti-tumor activation of Vγ9Vδ2 T-lymphocytes." (PMID 39107857, 2024).
oral cancer (4 papers, 2015 to 2023). "While ABCA1 increased level in colorectal and epithelial ovarian cancer is connected with worse prognoses for patients ⁠, the elevated ABCA1 level correlates with reduced tumor growth in colon and oral cancers." (PMID 37312227, 2023).
acute monocytic leukemia (3 papers, 2012 to 2021). Acute monoblastic leukemia (AML-M5), is one of the most common subtypes of acute myeloid leukemia (AML) that is either comprised of more than 80% of monoblasts (AML-M5a) or 30-80% monoblasts with (pro)monocytic differentiation (AML-M5b). "Furthermore, ABCA1 expression was inhibited by tar in human acute monocytic leukemia cell line THP-1-derived macrophages through the inhibition of liver X receptors." (PMID 25601961, 2015). "The 3H cholesterol efflux assay of IMB2026791 treated ABCA1-CHO cells and PMA induced THP-1 macrophages (human acute monocytic leukemia cell) further confirmed the compound as an accelerator of cholesterol efflux in a dose-dependent manner with an EC50 of 25.23 μM." (PMID 22399138, 2012).
chronic myelomonocytic leukaemia (3 papers, 2022 to 2025). "ABCA1 agonist erythrodiol restored cholesterol efflux in Listerin-deficient macrophages, while KO of ABCA1 abolished Listerin’s effects in Tsuchiya human monocytic leukemia line (THP-1) cells." (PMID 40526435, 2025). "Moreover, mutations in ABCA1 were found in patients with chronic myelomonocytic leukemia, suggesting that ABCA1 exerts tumor suppressor functions." (PMID 36395885, 2022).
cutaneous melanoma (3 papers, 2023 to 2025). A primary melanoma arising from atypical melanocytes in the skin. "We revealed a significant association between high ABCA1 expression and this prognostically unfavorable subtype of cutaneous melanoma (p < 0.001)." (PMID 37312227, 2023). "We first evaluated ABCA1 expression by immunohistochemistry performed on tissue microarrays generated from 110 primary cutaneous melanomas (archival formalin-fixed, paraffin-embedded specimens)." (PMID 37312227, 2023). "Increased ABCA1 reactivity in tumoral cells is a potential marker of nodular type of cutaneous melanoma." (PMID 37312227, 2023). "In cutaneous melanoma, we found a correlation between low ABCA1 expression and poor OS prognosis in SKCM patients (P = 0.034), and although the correlation was not high, this finding does not indicate that ABCA1 has low or even now association with the development of this tumour." (PMID 40297807, 2025). "Finally, survival analysis showed important impact of ABCA1 on long-term survival of cutaneous melanoma patients." (PMID 37312227, 2023). "Altogether, our in vitro results may help to understand the poor prognosis of patients and aggressiveness of primary cutaneous melanoma with high level of ABCA1." (PMID 37312227, 2023). "Enhanced expression of ABCA1 was also correlated with the presence of ulceration (p < 0.001), one of the most important negative histopathologic prognostic factors in cutaneous melanoma patients, and high mitotic activity of primary tumors (p < 0.001)." (PMID 37312227, 2023).
dyslipidaemia (3 papers, 2011 to 2025).
gastric adenocarcinoma (3 papers, 2023 to 2025). "In vitro, gastric adenocarcinoma cells with ABCA1 knockdown exhibited significantly inhibited proliferation and invasion properties." (PMID 40297807, 2025). "However, the biological effects and prognostic value of ABCA1 in gastric adenocarcinoma (GAC) remain unknown." (PMID 37874419, 2023).
Impaired glucose tolerance (3 papers, 2017 to 2022). An abnormal resistance to glucose, i.e., a reduction in the ability to maintain glucose levels in the blood stream within normal limits following oral or intravenous administration of glucose. "An earlier study on mice reported that the targeted deletion of β-cell ABCA1 caused an accumulation of cholesterol in islets as well as reduced glucose-stimulated insulin secretion (GSIS) and impaired glucose tolerance." (PMID 36553543, 2022).
multiple sclerosis (3 papers, 2024 to 2026). A progressive autoimmune disorder affecting the central nervous system resulting in demyelination. "It has been reported that in multiple sclerosis, myelin-induced elevation of Stearoyl-CoA desaturase-1 (SCD1) levels leads to a reduction in ABCA1 cell surface expression, affecting cholesterol efflux and promoting lipid accumulation." (PMID 39010173, 2024).
myeloproliferative diseases (3 papers, 2022 to 2024). "ABCA1 deficiency can accelerate myeloproliferative disorder; therefore, the overexpression of ABCA1 could be involved in the growth suppression of leukemic cells transwell cultured with MSC-H." (PMID 38731966, 2024).
Niemann-Pick disease, type C1 (3 papers, 2012 to 2020). Type C Niemann-Pick disease associated with a mutation in the gene NPC1, encoding Niemann-Pick C1 protein. "Accumulating evidence indicates that variants in genes such as ABCA1 (ATP-binding cassette, sub-family A, member 1) and NPC1 (Niemann-Pick disease, type C1) are related to CVD risk." (PMID 32824307, 2020). "Previous functional studies have shown that miR33a regulates expression of genes in cellular pathways of cholesterol transport, including ABCA1 (ATP binding cassette transporter) and the lysosomal transporter protein NPC1 (Niemann-Pick disease, type C1)." (PMID 22984453, 2012). "The genes contributing to these GO pathways in the DILGOM sample were ATP-binding cassette, sub-family G, member 1 (ABCG1), caveolin 1 (CAV1), Niemann-Pick disease, type C1 (NPC1), and Niemann-Pick disease, type C1, gene-like 1 (NPC1L1), while in the experimental SR study they were ABCA1 and NPC1." (PMID 27102866, 2016).
non-alcoholic fatty liver disease (3 papers, 2015 to 2021). "In addition, a study that included 391 Han Chinese adults showed that patients with the ABCA1 69CT or TT genotype had 0.68-fold lower risk of non-alcoholic fatty liver disease than those with the CC genotype." (PMID 33967955, 2021). "ABCA1 has not been previously associated with non-alcoholic fatty liver disease, AST or ALT levels, and no gene-diet interactions affecting transaminases were observed in the present study." (PMID 26579206, 2015).
psoriasis (3 papers, 2020 to 2023). An autoimmune condition characterized by red, well-delineated plaques with silvery scales that are usually on the extensor surfaces and scalp. "It is plausible to question if psoriasis-related inflammatory factors can interact with ABCG1 or ABCA1 to disrupt cholesterol metabolism and epidermal differentiation and exacerbate the inflammatory response." (PMID 37234169, 2023).
pulmonary arterial hypertension (3 papers, 2019 to 2022). Pulmonary arterial hypertension (PAH) is a group of diseases characterized by mean pulmonary artery pressure >20 mmHg and elevated pulmonary arterial resistance leading to right heart failure. "Research has shown that miR-20a-5p enhances the proliferation and migration of pulmonary artery smooth muscle cells and promotes the occurrence of pulmonary artery hypertension by targeting ABCA1." (PMID 35488248, 2022).
rheumatoid arthritis (3 papers, 2011 to 2022). A chronic, systemic autoimmune disorder characterized by inflammation in the synovial membranes and articular surfaces. "Staining for ACAT1 and ABCA1 in the rheumatic mitral valve was positive beside the rheumatoid nodule." (PMID 36307855, 2022). "This study demonstrated that clinical use of MTX for treating rheumatoid arthritis is associated with elevated expressions of atheroprotective protein HY27 and ABCA1 in human PBMCs." (PMID 21232092, 2011).
Splenomegaly (3 papers, 2012 to 2024). Abnormal increased size of the spleen. "Interestingly, combined deletion of bone marrow ABCA1 and ABCA7 causes severe splenomegaly associated with cellular lipid accumulation, a reduction in splenic CD3+ T cells, and induced markers of erythropoeisis." (PMID 22403608, 2012). "Interestingly, severe splenomegaly was observed in dKO transplanted mice, whereas no such phenotype was present in WT, ABCA1 KO, and ABCA7 KO transplanted mice." (PMID 22403608, 2012).
Stargardt disease (3 papers, 2011 to 2022). "Also, among the rare ABCA7 missense mutations, we observed mutations that affect amino acid residues that are conserved in ABCA1 and ABCA4, of which some correspond to established ABCA1 or ABCA4 disease-causing mutations involved in Tangier or Stargardt disease." (PMID 35361255, 2022).
uremia (3 papers, 2020 to 2025). A clinical syndrome associated with the retention of renal waste products or uremic toxins in the blood. "THP-1 cells treated with PMA and then exposed to uremia, showed increased ABCA1, CD36, and PLIN2 expression compared to macrophages exposed to normal serum." (PMID 33536542, 2021). "In another investigation, we found that serum albumin drawn from an animal model of uremia also renders macrophages vulnerable to endoplasmic reticulum stress and disturbs reverse cholesterol transport by impairing the ABCA1 expression and activity." (PMID 33019603, 2020). "Thus, this study investigates whether the pleiotropic actions of statins exert beneficial effects on vascular protection through potential modulation of ABCA1 transcription in the context of uremia." (PMID 40108621, 2025).
abdominal aortic aneurysm (2 papers, 2021). Enlargement and ballooning of the vessel that supplies arterial blood to the abdomen, pelvis and legs. "In abdominal aortic aneurysm tissues, mir-33 overexpression was found accompanied by decreased ABCA1." (PMID 34940525, 2021). "Its knockdown could inhibit abdominal aortic aneurysm development through ABCA1 expression and activation of the PI3K/Akt pathway." (PMID 33987194, 2021).
acute coronary syndrome (2 papers, 2021 to 2023). Signs and symptoms related to acute ischemia of the myocardium secondary to coronary artery disease. "For example, in some other diseases, ABCA1 has also been identified as a differentially methylated gene in acute coronary syndrome (ACS), and is strongly associated with epigenetic mechanisms in osteoarthritis." (PMID 36767748, 2023). "Consistent with the gradual severity of acute coronary syndrome, STEMI patients who survived presented higher ABCA1/G1-mediated macrophage cholesterol efflux than those who died." (PMID 34680453, 2021).
acute lung injury (2 papers, 2016 to 2020). A condition of lung damage that is characterized by bilateral pulmonary infiltrates (pulmonary edema) rich in neutrophils, and in the absence of clinical heart failure. "Triptolide can regulate ABCA1 gene and protein expression to promote the expression of ABCA1, reducing the secretion of inflammatory factors and alleviating the lung pathological injury associated with LPS-induced acute lung injury (ALI)." (PMID 32774439, 2020).
Alport syndrome (2 papers, 2021). A rare renal disease characterized by glomerular nephropathy with hematuria progressing to end-stage renal disease (ESRD), frequently associated with sensorineural deafness, and occasionally with ocular anomalies. "As the major regulator of cholesterol efflux in podocytes, ABCA1 deficiency is associated with podocyte lipid accumulation in glomerular diseases such as diabetic kidney disease (DKD), FSGS and Alport syndrome." (PMID 34442464, 2021). "In another study, we demonstrated that increased ABCA1 expression and induction of cholesterol efflux by SOAT1 inhibition is necessary to prevent renal injury in both DKD and Alport syndrome." (PMID 34442464, 2021).
anemia (2 papers, 2015 to 2019). A reduction in the number of red blood cells, the amount of hemoglobin, and/or the volume of packed red blood cells. "We observed, however, a significant association of this variant with severe anemia (p = 0.001), suggesting that ABCA1 is involved in the transport and metabolism of platinum or carboplatin, similar to its role in the transport of cholesterol." (PMID 25881102, 2015). "In particular, rs1128503 (ABCB1, C > T), rs12762549 (ABCC2, C > G), rs363717 (ABCA1, A > G) and rs11615 (ERCC1, T > C) were significantly associated with grade 3–4 anemia (p = 0.035, OR 1.58; p = 0.005, OR 0.55; p = 0.001, OR 1.31 and p = 0.024, OR = 1.58)." (PMID 25881102, 2015).
autoimmune uveitis (2 papers, 2022 to 2023). An autoimmune form of uveitis (disease). "An in vivo study has demonstrated the role of ABCA1 in the inhibition of ocular inflammation by activating liver X-receptor in autoimmune uveitis." (PMID 36980976, 2023). "ABCA1 was demonstrated to inhibit ocular inflammation via activation of liver X-receptor in an experimental model of autoimmune uveitis." (PMID 35719397, 2022).
breast tumor (2 papers, 2019 to 2023). "To test this, we examined whether expression of NR1H3/LXRA or NR1H2/LXRB correlated with expression of canonical LXR target genes (ABCA1 and APOE) in 81 ER-negative or 234 ER-positive primary breast tumours (obtained from TCGA dataset)." (PMID 31683867, 2019). "Vehicle control, GW3965, 26-OHC (the most abundant scOHC in breast tumour tissue) or 24,25-EC (the scOHC that elicited the greatest fold induction in reporter cells) were added to MDA-MB-468 or MCF7 cells for 4 or 16 h and changes to ABCA1 and APOE expression determined." (PMID 31683867, 2019).
Cirrhosis (2 papers, 2018 to 2023). A chronic disorder of the liver in which liver tissue becomes scarred and is partially replaced by regenerative nodules and fibrotic tissue resulting in loss of liver function. "Conclusively, this study declares that ABCA1 genotyping could be of great help in identifying cohorts with high risk of developing significant fibrosis with higher possibilities of progressing to cirrhosis with its morbid complications." (PMID 36444680, 2023).
colon adenocarcinoma (2 papers, 2019 to 2021). "To assess the clinical relevance of these findings, we interrogated the TCGA database for colonic adenocarcinoma and grouped patients based on their expression level of ABCA1." (PMID 31468706, 2019). "The proliferation, invasiveness, and migration of human ABCA1-transfected colon adenocarcinoma cells can be inhibited by downregulation of cyclooxygenase 2 (COX-2), caused either by simultaneous transgenic overexpression of apoAI or by exogenous treatment with human recombinant apoAI." (PMID 33805921, 2021).
COVID-19 (2 papers, 2023 to 2025). A disease caused by infection with severe acute respiratory syndrome coronavirus 2. "The results showed that TLR4 and ABCA1 had moderate to good diagnostic values in COVID-19 and AMI, with TLR4 performing better than ABCA1 (AUC in COVID-19: TLR4, 0.836; ABCA1, 0.775." (PMID 38022594, 2023). "We investigated these genes’ expression patterns further in the validation cohort and discovered that two genes, TLR4 and ABCA1, showed statistical differences in both the COVID-19 and AMI cohorts." (PMID 38022594, 2023). "In the bulk RNA-seq discovery cohorts for both COVID-19 and AMI, WGCNA’s intersection analysis and machine learning identified TLR4 and ABCA1 as significant hub genes, demonstrating high diagnostic and predictive value in the RNA-seq validation cohort." (PMID 38022594, 2023). "We found that TLR4 and ABCA1 were associated with the infiltration of various immune cells and were highly expressed in CD16 monocytes in severe COVID-19 patients." (PMID 38022594, 2023). "Therefore, TLR4 and ABCA1 were determined to be the most significantly correlated genes in common with COVID-19 and AMI." (PMID 38022594, 2023). "Consequently, further experimental evidence is imperative to ascertain the potentially pivotal role of ABCA1 in COVID-19-related AMI." (PMID 38022594, 2023). "Furthermore, we identify TLR4 and ABCA1 as potential contributors to the immune-related pathogenesis of COVID-19 with AMI." (PMID 38022594, 2023). "The dysregulation of TLR4 and ABCA1 may provide novel insights into the immune dysregulation and inflammatory response seen in COVID-19 and AMI cases." (PMID 38022594, 2023). "To investigate the expression patterns of ABCA1 and TLR4 in immune cells, we analyzed scRNA-seq data from PBMCs of COVID-19 patients and healthy controls." (PMID 38022594, 2023). "The heat map of gene-immune cell relationship revealed a positive link between ABCA1 and TLR4 in COVID-19 and AMI, particularly TLR4 with a range of immune cells including NK cells, neutrophils, eosinophils, dendritic cells, and macrophages." (PMID 38022594, 2023). "The hypermethylated genes with the lowest p values for hospitalized COVID-19 patients at inclusion (T1) vs. at 6 weeks post-inclusion (T2) were PARP9, ABCA1, MX1, OAS1, ARID5B, and the hypomethylated genes included TMEM131, ROCK1, IFNGR1, CFAP61, VRK2, and C6orf138." (PMID 41227320, 2025). "Nonetheless, we found no significant increase in ABCA1 levels in PBMCs from clinical COVID-19 patients with AMI." (PMID 38022594, 2023). "Furthermore, scRNA-seq analysis unveiled significant immune dysregulation in COVID-19 patients, characterized by altered immune cell proportions, phenotypic shifts, enhanced cell-cell communication, and elevated TLR4 and ABCA1 in CD16 monocytes." (PMID 38022594, 2023). "Lastly, the increased expression of TLR4, but not ABCA1, was validated in clinical blood samples from COVID-19 patients with AMI." (PMID 38022594, 2023). "No genetic causal link between COVID-19 and AMI and dysregulated TLR4 and ABCA1 may be responsible for the development of immune and inflammatory responses in COVID-19 patients with AMI." (PMID 38022594, 2023). "Additionally, TLR4 and ABCA1 showed significant upregulation specifically in CD16+ monocytes of COVID-19 patients, suggesting their potential involvement in the immune response during COVID-19." (PMID 38022594, 2023).
cyst (2 papers, 2020 to 2022). A sac-like closed membranous structure that may be empty or contain fluid or amorphous material. "This is further supported by our findings showing coexpression of MIF and ABCA1 in cyst-lining cells and correlating numbers of MIF- and ABCA1-positive cysts in kidneys with different genetic backgrounds and upon treatment with ICA." (PMID 32885302, 2020).